IL10 (interleukin 10)
Diseases named in the same sentence as IL10 in open-access papers (continued):
Sharing a sentence is not in itself a finding about the gene and the disease.
parasitemia (continued). "Interestingly, the expression of the anti-inflammatory cytokine il10 was significantly upregulated only in the WBC in the parasitemia stage." (PMID 40391212, 2025). "However, in the case of asymptomatic parasitemia, only 1 protein was significantly elevated at the time of diagnosis—IL-10." (PMID 41000872, 2025). "Altogether, these results support the hypothesis that high circulating levels of IL-10 protect μMT-/- mice against the deleterious effects of high parasitemia by suppressing proinflammatory cytokine expression." (PMID 40972121, 2025). "Consistent with this interpretation, IL10 blockade restored class-switched antibody production (measured at day 11), but this was not sufficient to substantially improve control of the first wave of parasitemia (peaking around day 7)." (PMID 41191641, 2025). "IL-10 was the cytokine that showed the highest correlation with parasitemia." (PMID 40743218, 2025). "Further, these cells may mediate both the tolerance and persistence of parasitemia through IL-10 and other mechanisms of immune regulation." (PMID 41000872, 2025). "Also, the reduction in latency is related to the increase in parasitemia in infected mice and low serum levels of IL10." (PMID 39703398, 2024). "Accordingly, neutralization of Q586B2 with newly generated nanobodies could hamper myeloid-derived IL-10 production and reduce parasitemia." (PMID 38413606, 2024). "In this context, we identified a series of anti-Q586B2 Nbs that could prevent the protein’s IL-10-inducing capacity and that could reduce first-peak parasitemia and prolong survival when administered to the infection site shortly after parasite inoculation." (PMID 38413606, 2024). "Conversely, at peak parasitemia on treatment day the cytokine profile for both studies is similar, including an increase in both IL-10 and IL-1RA levels that could reduce inflammation." (PMID 38890271, 2024). "Moreover, Omer and Riley demonstrated that TGF-β, in addition to increasing IL-10 concentration, improves survival and decreases parasitemia in Plasmodium berghei infected mice." (PMID 37628731, 2023). "Moreover, IL-10 was shown in other parasitic infections to contribute to the expansion and functional activation of CD8+ T cells." (PMID 35764965, 2022). "It was proved some time ago that IL-10-producing B cells are induced during parasite infection." (PMID 36618354, 2022). "The levels of IL-6 and IL-10 and the IL-10/TNF-α ratio were inversely associated with the age of the study participants in the absence of parasitic infections." (PMID 35421083, 2022). "The lower concentrations of TNF-α in this study cohort of children with parasitic infections may be due to their significantly higher concentrations of IL-10." (PMID 34539633, 2021). "Moreover, in Foxp3- CD4+ T cells that produce both IL-10 and IFN-γ (TR1 cells), Blimp1 is required to maintain IL-10 production during parasitic infections, as shown in murine models." (PMID 35154079, 2021). "The involvement of IL-10 in the proliferation of MCs was assessed using a T. spiralis infection model using Il10-/- mice of the C57BL/6 background; it was revealed that IL-10 KO resulted in a prolonged parasitic infection due to the reduction in MC proliferation and MCPT-1 production in MCs." (PMID 34067047, 2021). "The interplay between parasitemia, IL-10, IFN-gamma, and other mediators is important in determining patient outcomes during treatment, particularly in the control of pathological inflammatory responses and in the ultimate acquisition of immunological memory and protective immunity." (PMID 34351903, 2021). "In conclusion, the toxicity to T. cruzi and the production of IL-10 by infected PBMCs treated with MoFTI suggest that this molecule may be able to control parasitemia while regulating the inflammation, preventing the progress of Chagas disease." (PMID 32823803, 2020).
parasitemia (continued). "IL-10 plays a central role in suppressing inflammation through the inhibition of the production of pro-inflammatory cytokines, and expression is reported to increase in several fish species following LPS stimulation and bacterial and parasitic infections." (PMID 33521040, 2020). "Since antibodies are required to keep the parasitemia in check, the reduced B cell presence in the blood could in turn explain the higher parasitemia levels observed in TgAlbCre-IL10-/- mice at later stages of infection." (PMID 32012211, 2020). "The lack of IL-1β and TNF-α, both typically elevated in malarial disease, may also be due to downregulation by IL-10, which increases with rising parasitemia." (PMID 32958528, 2020). "IL-10 characterizes immune tolerance in a number of parasitic disease models." (PMID 32908913, 2020). "This is followed by the production of the anti-inflammatory cytokine IL-10, which is essential to dampen the inflammatory immune response after parasitemia has been cleared and to prevent tissue damage as well as death of the host due to a hyper-inflammation syndrome." (PMID 32012211, 2020). "Moreover, rosetting rates were also correlated with parasitemia, IL-6 and IL-10 levels in infected patients." (PMID 33028898, 2020). "Furthermore, using a generalized additive model and a likelihood ratio test to determine the impact of parasitemia on the secretion of these cytokines, parasitemia seems to be a major predictor of IL-10 and IL-6 levels." (PMID 33281757, 2020). "IL-10 has also been reported to promote hyper-parasitemia in mice infected with P. chabaudi adami." (PMID 30809232, 2019). "IL-12 and STAT4 are implicated in the regulation of NK cell IL-10 production during certain parasitic infections, but are not required for this response during Lm infection." (PMID 31552035, 2019). "In the present study, we investigated the role of B-1 cells in the maintenance of splenic IL-10 levels that could interfere with resistance to parasite infection." (PMID 28626451, 2017). "For example, Tenia solium CRT has been shown to elicit a TH2 response characterized by the induction of IL-10 during the parasite infection, which might contribute to the immune escape strategy developed by T. solium to suppress host immune response." (PMID 28620388, 2017). "The balance in interleukin (IL)-10/TNF-α rate could prevent increased parasitemia and host pathology." (PMID 28243235, 2017). "It is known that cytokines such as IL-10 can induce HLA-G expression by affecting mRNA transcripts and protein synthesis by human monocytes and trophoblasts, thus having a significant impact on parasitic infections." (PMID 29059176, 2017). "While IL10 can be produced by various cell populations, including B cells, monocytes, NK cells, Th2-type T cells, and Type 1 Tregs (Tr1 cells), several studies suggest that IFNγ+IL10+ Th1 cells are a particularly important source of IL10 in human and murine parasitic infections." (PMID 27802341, 2016). "Therefore, in cases of parasitic infections or tuberculosis, IL-10 is a critical biomarker for poor disease outcome." (PMID 27584662, 2016). "Cytokines with the greatest mediational impact on parasitemia were IL-4, IL-10, IL-12, and IFN-γ." (PMID 27418744, 2016). "In addition, IL-12-induced iNOS/NO responses in macrophages have been considered a novel mechanism of macrophage suppression, which is primarily mediated by IL-10 in certain parasite infection." (PMID 25687522, 2015). "In addition, in a cohort of patients with MS that presented with parasitic infections a lower number of relapses and increased levels of IL-10 and TGF-β were observed." (PMID 24919069, 2014). "IFNγ/IL-10 co-producing cells have been described in several parasitic infections and are hypothesized to be important in limiting CD4-mediated pathology, but they may also prevent the development of sterilizing immunity." (PMID 24415936, 2014).
parasitemia (continued). "IL-10 is a regulatory cytokine that performs crucial functions in parasitic infections." (PMID 25409540, 2014). "Furthermore, IL-10 and IL-6 positively correlated with parasitemia in immigrants and travelers, whereas IL-1β only correlated with parasitemia in immigrants, and IL-8 only in travelers." (PMID 23967342, 2013). "IL-10 and IL-6 levels correlated positively with parasitemias in immigrants and travelers." (PMID 23967342, 2013). "We examined the participation of IL-10 in the inhibition of CD4 T cell effector functions in our co-cultures because this cytokine is secreted by T cells with an effector phenotype in intracellular parasitic infections as well as by Tregs." (PMID 22545172, 2012). "As the T. cruzi bear several TLR-2 and -4 ligands and promote serum amyloid A production by macrophages, it is likely that during this parasite infection both signals cooperate to induce a proper environment for the induction of suppressor IL-10 producing neutrophils." (PMID 22577359, 2012). "Although it has long been recognized that IL-10-producing T cells could be generated in vivo during parasitic infection, it is only recently that the concept has emerged that specialized subsets of regulatory T cells contribute to this regulatory network." (PMID 22087344, 2011). "Despite the significant presence of the proinflammatory cytokines IFN-γ and TNF-α, the expression of the anti-inflammatory cytokine IL-10 may contribute to a balance that promotes parasitemia control while protecting the animal from the inflammatory effects of Th1 cytokines." (PMID 40743218, 2025). "In T. cruzi infection, treatment of IL-10–deficient mice with anti–IL-12 monoclonal antibody increased parasitemia, showing that IL-12, together with IFN-γ and TNF produced by innate immune cells, plays a pivotal role in controlling the parasitemia in early stages of infection." (PMID 34381739, 2021). "Low standing parasitemia seen with C9-M is attributed to the knock-out of PF3D7_1305500, which may have modulated the host immune response due to the higher secretion of immunoregulatory and anti-inflammatory cytokine, IL-10." (PMID 33013831, 2020). "No direct association between IL-10 and parasitemia was found." (PMID 33028898, 2020). "It was confirmed that cytokines such as IL-12, TNF-α, IFN-γ, and IL-2 play an important role in controlling the proliferation of Babesia in the early and acute stages of infection, while IL-10, IL-4, IL-5, and IL-6 may involve in chronic and low parasitemia stages of infections." (PMID 32733477, 2020). "However, parasitemia and IL-10 correlated with rosetting frequency." (PMID 33028898, 2020). "However, in the face of parasitic infection an acute inflammatory response is necessary to control the parasite proliferation, hence, the anti-inflammatory role of IL-10 may help the disease progression." (PMID 31024534, 2019). "Moreover, we have observed unaltered placental levels of type 1 cytokines and a significant increase in IL-10 levels, associated with the presence of leukocytes and frequent absence of parasitemia." (PMID 31805150, 2019). "Here, the IL-10 level was found to gradually increase after infection, which might result in decreases of several pro-inflammatory cytokines, leading to high parasitemia and severe anemia." (PMID 31711531, 2019). "Thus, the increased levels of IL-10 and TGF-β might correlate with host susceptibility to parasitic infection." (PMID 28784165, 2017). "The aim of this study was to investigate L. infantum-specific IFN-γ and IL-10 production in stimulated blood in dogs with clinical leishmaniosis at the time of diagnosis and correlate these with disease severity, the humoral immune response and blood parasitemia." (PMID 27260142, 2016).
parasitemia (continued). "The innate target cells could be macrophages themselves (being infected by LCMV) which are modulated by IL-10 such that they would better sustain viral replication, potentially by inhibition of NO production as it was shown for parasite infection or by inhibition of TNF-α and IFN-γ production." (PMID 24244162, 2013). "Also, IL-10 production was predominantly increased during parasite infection." (PMID 23071588, 2012). "During the study, the animals exhibited four parasitemia peaks concomitant with the cytokines IFN-γ and IL-10." (PMID 40743218, 2025). "The phenomenon of T-cell exhaustion, which can be seen in advanced disease, features low IL-2 levels alongside high IL-10 and TGF-β production by lymphocytes, as described in other viral and parasitic diseases." (PMID 40909167, 2025). "The IL-10 from CD4+ and CD8+ cells in parasitic diseases has been described as delaying control while generating immunity due to treatments or vaccination." (PMID 40006676, 2025). "This was attributed to the activation of the inflammatory cascade induced by parasitic infection, and TNF-α stimulated the production of inflammatory cytokines (IL-3, IL-6, and IL-10)." (PMID 40007749, 2025). "Participants with high parasitemia had raised TNF‐α (p < .001), IFN‐ɣ (p < .001), IL‐1β (p < .001), IL‐6 (p < .001), GM‐CSF (p < .001), and IL‐10 (p < .001), but reduced IL‐3 (p < .001) and TGF‐β (p < .001) than those with low parasitemia." (PMID 39240033, 2024). "The results demonstrated the antimalarial potential of FDMEp and eleuterol, reducing parasitemia, increasing survival time, reducing INF-γ, and elevating IL-10." (PMID 39703398, 2024). "EEEp and isoeleutherin also reduced parasitemia and INF-γ to a lesser extent, with an increase in IL-10." (PMID 39703398, 2024). "In individuals with P. vivax infections and high parasitemia, a moderate to strong correlation was observed between IL-6, IL-10, and MCP-1, highlighting the importance of the IL-6/MCP-1/IFN-γ axis in regulating parasitemia in P. vivax infection." (PMID 39567619, 2024). "Various clinical parameters, echocardiography findings, parasitemia status, brain natriuretic peptide (BNP) and troponin T (TnT) levels, and inflammatory biomarkers (IL-6, IL-10, IL-12p70, IL-17A, adiponectin, and IFN-γ) were assessed." (PMID 38109427, 2023). "In contrast, alternatively activated M2 macrophages play a pivotal role in immune suppression, wound healing, and fibrosis, and are induced by parasitic infections, immune-suppressive cytokines (e.g., IL4, IL10, IL13), and glucocorticoids." (PMID 36552868, 2022). "In Mcpt4+/+ mice, parasitemia is the overwhelming focal point of the host immune response, with correlations between type 1 (IFN-γ) and type 2 (IL-10 and IL-13) cytokines and chemokines as well as MPO." (PMID 35154114, 2022). "In response to parasitic infections, activated CD4+ Th9 cells can generate the anti-inflammatory cytokine IL-10, which is involved in the maintenance and reestablishment of host immunity." (PMID 35693811, 2022). "16S copy numbers were also directly and weakly negatively correlated with plasma IL-4 and MCP-1, whereas parasitemia was directly and strongly positively correlated with plasma MIP-1α, and directly and weakly positively correlated with plasma IL-10." (PMID 35970557, 2022). "Thus, we speculate that the key immunomodulatory role of the cytokines TGF-β and IL-10 and the essential regulation of T cells including Treg cells by TGF-β might initially be linked molecularly at least during the early phase of parasite infections with HLA-G levels." (PMID 35204759, 2022). "Animal studies have found higher parasitemia and mortality among protein-restricted diet feed mice and impaired inflammatory immune response (lower macrophage activation of TNF-a, IL-10, and NO)." (PMID 34067079, 2021).
parasitemia (continued). "Blocking the IL-10 receptor (IL-10R) during parasite infection demonstrated that the presence of splenic Tregs and peritoneal APC expressing HO-1 were both dependent on IL-10 activity." (PMID 34943041, 2021). "The aim of this study was to measure the serum proinflammatory (IL-12, GM-CSF & IFN-γ) to anti-inflammatory (IL-10, IL-4) cytokine ratio, oxidant (MDA) level and antioxidant enzyme (SOD; GPx) activities after blood parasite infections." (PMID 34438696, 2021). "Upon parasite infection, levels of pro- and anti-inflammatory cytokines TNF-α, IFN-γ, IL-10, and IL-4 were increased by 7.0, 10.0, 14.0, and 1.5 times, respectively, in the systemic blood circulation of infected mice." (PMID 33803419, 2021). "CD16+ DCs isolated at peak parasitemia also had increased functionality during in vitro restimulation with iRBCs, with increased TNF production by both TNF-only and TNF/IL-10 producing CD16+ DCs." (PMID 31900030, 2020). "These B cells responded differentially to parasite infection and a previous report supports this finding by showing that PerC B cells activated by anti-CD40 and LPS secreted more IL-10 and IL-6 compared to splenic B cells." (PMID 32197642, 2020). "At peak parasitemia, there was a significant increase in TNF/IL-10 coproduction in response to in vitro pRBC restimulation (P = .04), with no significant changes in single TNF or IL-10 production." (PMID 30239833, 2019). "IL-27 plays a critical role in the induction of IFN-γ and IL-10 from CD4+ T-cells, and suppression of inappropriate Th17 development to achieve immune-balance during intracellular parasite infections." (PMID 31024534, 2019). "Meanwhile, in mice infected with P. yoelii, production of IL-10 and TGF-β were believed to correlate with high parasitemia and severe anemia." (PMID 31711531, 2019). "To further investigate the requirements for sustained cellular immunity to an intracellular parasitic infection, we assayed the contribution of CD4+ and CD8+ T cells to the production of IFN-γ, TNF-α and IL-10 in spleen cells of post-challenged animals." (PMID 31739549, 2019). "In a lethal P. yoelii infection in mice, production of IL-10 and TGF-β were thought to inhibit pro-inflammatory responses, and this was correlated with high parasitemia and severe anemia." (PMID 30809232, 2019). "For example, parasite infection (Nb) and mite allergen (HDM) induced predominantly IL-10-producing LAG3+CD49b+ T cells that are CD4+ with very few that are CD8+." (PMID 30510554, 2018). "In this research, rHcSTP-1 protein showed a significant Th2 type immune response by decreased IL-10 cytokine in culture PBMCs, and thus exerts suppressive potential on differentiation of Treg cells, which might be immune modulatory role of HcSTP-1 against parasite infection." (PMID 30061894, 2018). "Overexpression of regulatory cytokine genes in Tregs, such as IL-10 and TGF-β, characterizes immune tolerance in a number of parasitic disease models." (PMID 30037796, 2018). "We analyzed parameters related to parasitemia, plasma levels of TNF, IL-10, and CCL2, and cardiac histopathology after the administration of carvedilol for 30 days." (PMID 28377930, 2017). "Accordingly, while the CD4+ T cells from 103 parasite infection (LdWTLLO) continued to produce IFN-γ 21 days postinfection, very low levels of IL10 were observed in this group." (PMID 29312315, 2017). "LSA IFN-γ concentration was negatively correlated with blood parasitemia and antibody levels and positively correlated with ConA IFN-γ and LSA IL-10 concentrations." (PMID 27260142, 2016). "The modeling identified IL-4, IL-10, IL-12, and IFN-γ as the strongest mediators between infection status and parasitemia, with paired contrasts from the analysis indicating that IL-4 had the largest mediational effect." (PMID 27418744, 2016).